EIF5A2 (eukaryotic translation initiation factor 5A2)
Diseases named in the same sentence as EIF5A2 in open-access papers (continued):
Sharing a sentence is not in itself a finding about the gene and the disease.
cancer (continued). "eIF5A2 on human chromosome 3q26.2 has been identified as a novel oncogene in cancer." (PMID 27028999, 2016). "Moreover, in many cancers, eIF5A2 plays a vital role in EMT progression by transcriptional inhibition of different downstream molecules." (PMID 27028999, 2016). "Further, genome-wide gene expression analysis in EphA6 knock-down cells identified a panel of differentially regulated genes including PIK3IPA, AKT1, and EIF5A2, which could contribute to EphA6-regulated cancer progression." (PMID 26041887, 2015). "Both in vitro and in vivo studies suggest that eIF5A2 could promote cancer cell proliferation and increase cancer cell metastasis." (PMID 26581310, 2015). "Taken together, ablation of EIF5A2 may represent a promising anti-cancer strategy, targeting the crossroads of angiogenesis and metastasis in HCC." (PMID 25071013, 2014). "Chromosome 3q amplification leads to up-regulation of eIF5A2 in cancers, disturbing the well-regulated translational level maintained by eIF5A1 and leading to aberrant activation of protein synthesis pathway; as the result, normal cells are transformed to more aggressive cancerous cells." (PMID 23029619, 2012). "This suggests that eIF-5A2 overexpression alone does not increase the susceptibility of cancer onset in mice." (PMID 21612665, 2011). "The functions of eIF-5A2 are mainly revealed in cancer initiation and progression." (PMID 21612665, 2011). "Thus, EIF5A2 is a potential prognostic biomarker for cancer." (PMID 40964657, 2025). "Moreover, TCGA analysis revealed that EIF5A2 was significantly upregulated in 27 types of cancer, with overexpression being linked to shorter OS in three, worse DFS in two, and worse PFS in six types of cancer." (PMID 38770178, 2024). "Furthermore, we used the GEPIA online tool to assess EIF5A2 expression across 31 types of cancers." (PMID 38770178, 2024). "Indeed, eIF5A2 showed mRNA over-expression in most of these cancer types." (PMID 36848144, 2023). "Thus, we speculated that EIF5A2 might promote the tumor initiation and cancer stemness of EOC cells by activating KLF4 expression." (PMID 33726845, 2021). "Thus eIF5A-2 overexpression increases growth, glucose uptake and lactate secretion by up-regulating glycolytic enzymes, which is precisely the metabolic reprogramming that occurs in most cancer cells." (PMID 33379337, 2020). "Therefore, we hypothesized that the up-regulation of EIF5A2 directly mediates miR-203-medicated cancer biology." (PMID 27376958, 2016). "Because drug resistance is one of the characters of cancer stem cells and a multiple drug-resistant transporter gene increased in the EIF5A2 overexpressed cells, we next investigated whether EIF5A2 overexpression contributes to the chemoresistance of ESCC cells." (PMID 26317793, 2015). "However, the role of RPL22L1 during mRNA decoding with eIF5A2 in cancer cells remains unclear." (PMID 40617352, 2025). "Specifically, miR‐146a‐5p has been reported to bind directly to WNT2, EGFR, NOTCH2, TRAF6, IRAK1 and EIF5A2 to inhibit EMT and act as a tumour suppressor in various human cancers." (PMID 40785027, 2025). "We examined the relationship between EIF5A2 and immune checkpoints using Spearman analysis and found that EIF5A2 was correlated with CD274, PDCD1LG2, and HAVCR2 in the majority of cancers and PDCD1, CTLA4, LAG3, SIGLEC15, and TIGIT in some tumors." (PMID 40964657, 2025). "EIF5A2 induces epithelial-mesenchymal transition (EMT), promoting tumor formation, enhancing cancer cell growth, and increasing cancer cell motility and metastasis." (PMID 39108268, 2024). "Recently, EIF5A2 contributes to enhancing the EMT process of tumors, resulting in the progression and metastasis of cancers." (PMID 37598186, 2023). "Altogether the genomic data from the Cancer Genomics Portal, together with individual analysis from 7 LUAD patients suggest that eIF-5A2 enhanced expression shows strong correlation with bad prognosis." (PMID 36915194, 2023).
cancer (continued). "EIF5A2 has the effect of enhancing the EMT and stemness of tumors, which promotes the progression, recurrence and metastasis of cancers." (PMID 36290289, 2022). "EIF5A2, a second isoform of EIF5A, has been observed to be up-regulated in many type tumors and is an important carcinogenic biomarker in many cancers." (PMID 33308276, 2020). "Inhibition of eIF5A2 activity by N1-guanyl-1, 7-diaminoheptane (GC7), an inhibitor of deoxyhypusine synthase, has strong anti-tumor effects on human cancer cells." (PMID 27028999, 2016). "Result showed that blockade of EMT with Twist siRNA abolished the regulatory effects of eIF5A2 on cancer cell chemoresistance to doxorubicin, suggesting that EMT was mainly responsible for eIF5A2-mediated chemoresistance." (PMID 26581310, 2015). "Here, we found that eIF5A2 is regulated by polyamines at the translational level and that eIF5A2, rather than eIF5A1, is important for cancer cell growth." (PMID 40617352, 2025). "EIF5A2 is a promising candidate as a prognostic marker for cancer, but the findings from previous studies have not been consistent, making it difficult to establish its predictive significance definitively." (PMID 38770178, 2024). "In mammals, the main isoform, eIF5A1 (generally called eIF5A), is constitutively expressed in all cells and tissues, whereas the second isoform, eIF5A2 protein, is not normally detectable, except in certain cancer cells." (PMID 34273022, 2022). "In conclusion, our study demonstrated the molecular mechanisms by which EIF5A2 regulates stem-like properties in EOC, further broadening the insight of the mechanisms regulating cancer stem cells and suggesting a promising CSCs-specific therapeutic target, EIF5A2, for future treatment of EOC." (PMID 33726845, 2021). "EIF5A2 regulates invasion and migration via regulation of EMT in various cancer cells." (PMID 34864817, 2021). "Significantly, cancer cells on either 2-dimensional (2D) or 3D and non-malignant cells on 2D plastic do not produce NO and upregulate negative players: NFκB, EIF5A2, SCA1 and MMP-9 — that disrupt the network." (PMID 29560860, 2018). "As a result, there is no spontaneous tumor formation in eIF-5A2 mice, and they are not cancer-prone, and they do not respond to cancer reagents." (PMID 21612665, 2011). "In addition, silencing eIF5A2, rather than eIF5A1, strongly inhibits cancer cell growth, and genes upregulated by eIF5A2 are distinct from those upregulated by eIF5A1." (PMID 40617352, 2025). "The results showed that the level of EIF5A2 was higher in 374 cancer than 50 normal sample in LIHC.To confirm whether EIF5A2 was the genuine target gene of miR‐383, we first examined the protein and mRNA expression of EIF5A2 in HCC cell lines." (PMID 30801960, 2019). "Notably, eIF5A2, but not eIF5A1, was found to play a major role in human cancer cell proliferation." (PMID 40617352, 2025). "EIF5A2, a key member of the EIF family, has not been extensively studied regarding its role and mechanism in pan-cancer." (PMID 40964657, 2025).
tumor (52 papers, 2011 to 2025). "Spearman correlation analysis was used to estimate the relationship between EIF5A2 expression and tumor mutation burden (TMB), microsatellite instability (MSI), and immunologic features." (PMID 40964657, 2025). "As previously discussed, EIF5A2 has been implicated in tumor initiation, progression, metastasis, and chemotherapy resistance, making it a promising prognostic marker for solid malignancies." (PMID 38770178, 2024). "In terms of tumor types, high EIF5A2 expression was associated with poor OS in digestive system tumors, with an HR of 1.89 (95% CI: 1.57–2.27)." (PMID 38770178, 2024). "EIF5A2 is overexpressed in many human malignancies and is critically associated with tumor progression, lymph node metastasis, and poor prognosis." (PMID 27203388, 2016). "EIF5A2 has been implicated as a key contributor to cell motility and tumor metastasis in diverse cancers." (PMID 27376958, 2016). "Correlation analysis of clinicopathological characteristics and eIF5A2 expression showed that the expression of eIF5A2 was closely associated with node metastasis, distant metastasis, and tumor-node-metastasis staging." (PMID 27028999, 2016). "Tumor cells were transfected with eIF5A2 siRNA or plasmid encoding eIF5A2 to down- or up regulate the expression of eIF5A2." (PMID 26581310, 2015). "In HCC, eIF5A2 expression is associated with adverse prognosis such as presence of tumor metastasis and venous infiltration." (PMID 23029619, 2012). "In consistence with these findings, another study using quantitative polymerase chain reaction reported a reciprocal association between up-regulation of eIF5A2 with tumor metastasis and encapsulation." (PMID 23029619, 2012). "Further studies of EIF5A2 associated with tumor metastasis have indicated EMT as the major pathway." (PMID 32605067, 2020). "In addition, this study sheds light on the molecular mechanisms underlying the effects of EIF5A2 on tumor angiogenesis and vasculature remodeling." (PMID 25071013, 2014). "This perspective aligns with findings in the tumor microenvironment, where EIF5A2 has been shown to promote cell migration and enhance survival signals." (PMID 41358199, 2025). "There was a correlation between EIF5A2 expression and tumor size, tumor grade, and TNM stage in LIHC." (PMID 40964657, 2025). "Inhibition of EIF5A2 has been shown to suppress tumor development and metastasis, while also overcoming chemotherapy resistance." (PMID 38770178, 2024). "Given the critical involvement of EIF5A2 in tumor-specific mechanisms such as EMT, autophagy, and drug resistance, it represents a promising target for developing novel therapeutic approaches." (PMID 38770178, 2024). "The ubiquitination of EIF5A2 mediated by HERC3 repressed tumor cell invasion and migration in colorectal cancer." (PMID 38584230, 2024). "We found that 9% of the tumor samples displayed amplification and high mRNA levels of EIF5A2, while 5% showed high levels of mRNA and deep deletion for EIF5A1 gene." (PMID 36915194, 2023). "Next, we performed immunohistological analysis to evaluate the levels of eIF-5A2 protein and its localization in biopsy tumor tissue samples and normal adjacent tissue from 7 patients with early stage LUAD." (PMID 36915194, 2023). "Two human genes encode eIF-5A, being eIF5-A1 constitutively expressed whereas eIF5-A2 is frequently found overexpressed in human tumours." (PMID 36915194, 2023). "Combined treatment using eIF5A2-targeted downregulation together with cisplatin significantly inhibited tumor growth compared with cisplatin alone in the subcutaneous mouse model." (PMID 35931669, 2022). "Immunohistochemistry (IHC) was used to explore eIF5A2 levels in tumor and normal tissues of two patients with NSCLC using an eIF5A2 monoclonal antibody." (PMID 35931669, 2022). "Among these signaling pathways, Notch1/Hes1 which plays a crucial role in tumor development can be activated by EIF5A2." (PMID 33726845, 2021).
tumor (continued). "EIF5A2 staining was strong in the cytoplasm of tumor cells but remained weak in the adjacent normal tissues." (PMID 33827661, 2021). "Up to now, there are few reports on the association between EIF5A2, HGD, HS6ST1, PLS1, PTHLH, and YEATS2 methylation modification and tumor." (PMID 34796198, 2021). "In vivo, EIF5A2 depletion in the 779E cells reduced tumor growth, while EIF5A2 overexpression in PANC1 cells enhanced tumor growth." (PMID 32368188, 2020). "In the meanwhile, the level of miR-218-5p and EIF5A2 in the tumor tissues was determined and results indicated that circ_0003998 knockdown elevated miR-218-5p and reduced EIF5A2 expression in vivo." (PMID 33308276, 2020). "High tumor expression of EIF5A2 was prone to the expression of low E-cadherin and high beta-catenin (p = 0.046 and p = 0.020, respectively)." (PMID 32605067, 2020). "EIF5A2 participates in many biological processes of tumor cells, including growth, metastasis and EMT." (PMID 32466797, 2020). "Restoration of EIF5A2 or SCA1 severely impaired tumor-cell reversion, validating the importance of the inactivation of these two target genes for normal functional differentiation of breast acini." (PMID 29560860, 2018). "Cell motility assay, tumor growth assay and cytotoxicity assay were performed on the EIF5A2 overexpressed cells and control cells." (PMID 27549330, 2016). "The protein levels of eIF5A2 in tumor and adjacent tissue samples from 90 HCC patients with detailed clinical, pathological, and clinical follow-up data were evaluated." (PMID 27028999, 2016). "Compared with the adjacent non-tumor mucosal tissues, the EIF5A2 mRNA was significantly upregulated in 72 CRC tissues and this upregulation was strongly correlated with the downregulation of miR-203." (PMID 27376958, 2016). "In conclusion, our data further confirmed that miR-203 suppressed tumor growth and invasion by repressing EIF5A2 expression." (PMID 27376958, 2016). "Consistent with previous results, we found that EIF5A2 mRNA expression was significantly higher in the CRC tissues than that in the non-tumor mucosa tissues." (PMID 27376958, 2016). "Eukaryotic translation initiation factor 5A2 (eIF5A2) has been identified as a critical gene in tumor metastasis." (PMID 27028999, 2016). "It was also reported that silencing of endogenous EIF5A2 increased tumor perfusion by remodeling tumor vessels, thus increased the chemosensitivity of HCC cells to 5-FU in vivo." (PMID 26317793, 2015). "EIF5A2 overexpression was found in 75 of the tumor specimens, compared with only seven of 160 matched adjacent non-tumor mucosal tissues (P<0.001)." (PMID 25793713, 2015). "Eukaryotic translation initiation factor 5A2 (EIF5A2) plays an important role in tumor progression and prognosis evaluation." (PMID 25793713, 2015). "This study aimed to investigate the function of EIF5A2 in tumor progression and its potential mechanisms." (PMID 25793713, 2015). "Compared with the control group, the EIF5A2 knockdown group showed lower micro-vessel density (MVD) as determined by CD34 immunostaining of tumor sample sections." (PMID 25071013, 2014). "In this study, the influences of EIF5A2 on angiogenesis, vascular structure, vessel function and tumor microenvironment in HCC were evaluated using both in vitro and in vivo approaches." (PMID 25071013, 2014). "Several studies have found that N1-guanyl-1,7-diaminoheptane (GC7) suppresses tumor cell proliferation by inhibiting eIF5A-2." (PMID 25380840, 2014). "Both in vitro and in vivo assays indicated that ablation of endogenous EIF5A2 inhibited tumor angiogenesis by reducing matrix metalloproteinase 2 (MMP-2) expression." (PMID 25071013, 2014). "EIF5A2 silencing was found to remodel tumor vasculature, increase blood perfusion and sensitize tumor cells to chemotherapeutic agents." (PMID 25071013, 2014). "Fluorescent immunostaining of tumor sections indicated that EIF5A2 downregulation increased tumor perfusion while reducing blood leakage." (PMID 25071013, 2014).
tumor (continued). "Tumor blood vessel flow, as measured by laser Doppler imaging, was significantly increased in the EIF5A2-silenced group compared to the NC control group." (PMID 25071013, 2014). "In this study, we show for the first time that the ablation of endogenous EIF5A2 can improve tumor oxygenation and sensitizes to chemotherapy by remodeling tumor vasculature." (PMID 25071013, 2014). "Compared with the control group, tumor micro-vessels in xenografts from EIF5A2 knockdown tumor cells exhibit more continuous and smooth wall, more regular endothelial lining, and morphology similar to normal vasculature." (PMID 25071013, 2014). "Using semi-quantitative RT-PCR and real-time PCR analysis, we demonstrated that EIF5A2 was frequently over-expressed in human HCC tumor tissues compared to matched healthy counterparts." (PMID 25071013, 2014). "CD34 and collagen IV co-staining of xenograft tissue sections and human HCC tissue sections demonstrated that tumor vessel walls in the EIF5A2 low expression group were more smooth and continuous." (PMID 25071013, 2014). "Taken together, our results indicate that EIF5A2 silencing increases tumor vessel wall continuity, increases blood perfusion and improves tumor oxygenation." (PMID 25071013, 2014). "In the transplantation model of heterogeneous tumor within mouse, the overexpression of EIF5A2 stimulated tumor growth." (PMID 22734884, 2012). "This aberrant expression of eIF5A2 was positively correlated with advanced tumor stage and also indicated poor prognosis for early stage NSCLC patients." (PMID 23029619, 2012). "Clinical studies have demonstrated a correlation between up-regulation of eIF5A2 level with tumor metastasis and venous infiltration." (PMID 23029619, 2012). "Instead of resulting in spontaneous tumor formation, overexpression of eIF-5A2 accelerated the aging process in adult transgenic mice." (PMID 21612665, 2011). "As an oncogene, EIF5A2 can promote the growth, invasion, and metastasis of tumor cells." (PMID 40964657, 2025). "Furthermore, RAD51-AS1 interacted with miR-140-3p, leading to the upregulation of EIF5A2, with the outcome of promoting tumor growth in OvCA." (PMID 38584230, 2024). "Furthermore, an in vivo subcutaneous model showed that a combination of eIF5A2 downregulation and cisplatin markedly inhibited tumor growth compared with cisplatin treatment alone." (PMID 35931669, 2022). "Upregulated eIF5A2 triggers autophagy via an as-yet-unknown mechanism, thereby protecting tumor cells from cisplatin toxicity." (PMID 35931669, 2022). "We propose that inhibition of EIF5A2 maturation using GC-7 may suppress tumor metastasis by reversing EMT." (PMID 33827661, 2021). "Enhanced eIF5A2 has reported to initiate tumor formation, promote tumor cell metastasis and promote drug response, suggesting that targeting eIF5A2 could inhibit tumorigenesis and metastasis as well as enhances the sensitivity of drugs." (PMID 33200656, 2020). "In addition, ablation of endogenous EIF5A2 inhibited tumor angiogenesis by reducing MMP-2 expression." (PMID 32522053, 2020). "The BCPAP/eIF5A2 shRNA groups had less tumor mass compared to the BCPAP/NC shRNA groups." (PMID 33200656, 2020). "Also, previous studies probed that EIF5A2 was involved in the progression of HCC by regulating tumor cell metabolic reprogramming, migration, invasion, proliferation, and oxidative stress." (PMID 33308276, 2020). "Notably, patients with regional lymph node metastasis tended to have higher tumor EIF5A2 expression (73.1%, p = 0.008)." (PMID 32605067, 2020). "In particular, eIF5A2 plays an important role in regulating tumor growth, invasion and metastasis." (PMID 32522053, 2020). "Therefore, circ_0003998 knockdown enhanced DOX-mediated repression of HCC tumor growth by regulating miR-218-5p/EIF5A2 in vivo." (PMID 33308276, 2020). "We therefore concluded that therapies targeting the eIF5A2 signaling pathway may be more effective to prevent organ metastasis and primary tumor formation." (PMID 32522053, 2020).